IL6 (interleukin 6)
Diseases named in the same sentence as IL6 in open-access papers (continued):
Sharing a sentence is not in itself a finding about the gene and the disease.
melanoma (continued). "Also, it was shown that ILs play a crucial role in the pathogenesis of melanoma by driving inflammation and expanding MDSCs, with IL-1β and the downstream IL-6/STAT3 axis being key contributors to this process." (PMID 40636453, 2025). "Although the relationship between HLA-G and IL-6 is not clear in some cancer types, in melanoma, IL-6 signaling associated with HLA-G expression seems to amplify immunosuppression and cancer evasion." (PMID 41268555, 2025). "On the other hand, for the melanoma group we observed that serum IL-6 increased concentrations when the participants experienced a prior oncological disease (p=0.02) and males showed less int-IL-6 than females (p=0.03)." (PMID 41268555, 2025). "Moreover, IL-6 serves as a serum biomarker of significant clinical value for melanoma prognosis and predicting immune therapy response." (PMID 40699636, 2025). "Notably, IL-6 secreted by CCNB1-high melanoma cells not only maintains STAT3 activation within tumor cells but also enhances STAT3 signaling in NK-92MI cells, potentially exacerbating NK cell dysfunction." (PMID 40430484, 2025). "Notably, an analysis of patients with melanoma in the CheckMate-067 trial revealed that elevated IL-6 was an independent predictor of poor survival among those treated with nivolumab and ipilimumab." (PMID 40091005, 2025). "Elevated baseline levels of cytokines in melanoma patients have been mainly studied for IL-6 and IL-10, with elevated initial levels of IL-10 being associated with increased mortality, while a progressive increase in IL-6 predicts a worse prognosis in melanoma." (PMID 40004863, 2025). "IL-6 plays a complex, dual role in melanoma initiation, progression, and treatment response." (PMID 40699636, 2025). "More critically, these T cells secrete elevated levels of pro‐inflammatory cytokines such as IFN‐γ, TNF‐α, and IL‐6, which can support tumor‐promoting inflammation and alter the balance of immune‐stimulatory versus suppressive cues in the melanoma microenvironment." (PMID 40926366, 2025). "Therefore, IL-6 plays a dual role in melanoma; it can have antitumor effects in some cases but tends to promote tumor cell survival and invasion during disease progression or metastasis." (PMID 40699636, 2025). "However, research by Lise Hoejberg indicated that IL-6 generally exhibits a protumor effect in patients with melanoma, particularly during advanced or metastatic stages." (PMID 40699636, 2025). "To address the possible role of endogenous, physiological oncogenic GLI activity, we performed RNA-interference (RNAi)-mediated GLI1 inactivation in human BRAFV600E mutated melanoma cells (WM35) and treated the cells with IL6 [75 ng/mL] for 18 h to activate IDO1 expression via STAT3." (PMID 39962447, 2025). "Cells treated with conditioned medium from melanoma stem cells had increased ROS production, neutrophil extracellular trap release and greater secretion of matrix metalloproteinase 9 and the pro-tumorigenic cytokines IL-6 and IL-8." (PMID 39825956, 2025). "An analysis of baseline blood samples from 140 melanoma patients treated with anti-CTLA-4 therapy found that only low baseline IL-6 levels (< 2.5 ng/L) and female sex were correlated with an increased risk of Grade ≥ 3 irAEs after adjustment for follow-up time." (PMID 40632185, 2025). "Furthermore, melanoma MeWo cells exposed to physiological levels of ceramides (ceramide-MeWo) increased IL-6 secretion and shifted metastatic tropism to the liver." (PMID 40280124, 2025). "Interestingly, in vitro and in vivo experiments have validated that DHA reduces the expression of IL-10 and IL-6 proteins in melanoma and inhibits the phosphorylation of STAT3 to induce mitochondrial apoptosis." (PMID 41160271, 2025).
melanoma (continued). "Adipocytes in obese patients with melanoma release high amounts of pro-inflammatory cytokines and growth factors (IL-6, IL-32 or TNF-α) and molecules involved in the angiogenesis enhancement (OPN—osteopontin, chemerin, apelin and PAI-1) that modulate melanoma proliferation." (PMID 40136652, 2025). "In addition, we simulated the effect of IL-6 secreted by melanoma on CD4+ T cells present in the TME (right)." (PMID 39544930, 2024). "In addition, the CpG-sEV assembly significantly prolonged the residence time, and elicited elevated cytokine and chemokine levels, such as IL-6, IL12-p40, and CXCL5, along with increased Th1-associated IgG2a antibody specific to B16BL6 melanoma in vivo." (PMID 39174509, 2024). "The simulations propose that IL-6 secreted by high-E2F1 melanoma cells is sufficient to trigger the activation of the IL-6/IL6R/STAT3 axis in CD4+ immune cells, which could also trigger secretion of other inflammatory factors." (PMID 39544930, 2024). "There are two trials that will test the addition of the IL-6 inhibitor tocilizumab to ipilimumab/nivolumab in patients with advanced melanoma to observe for differences in PFS/OS while monitoring the toxicity and development of adverse events (NCT03999749 and NCT04940299)." (PMID 38791970, 2024). "Also, the coculture system indicates that IL-6 secreted by melanoma cells to the tumor niche activates in a paracrine manner CD4+ cells in their vicinity." (PMID 39544930, 2024). "Importantly, IL-6 levels considerably increased when cancer and immune cells were cultured together, suggesting a positive feedback loop between melanoma and T cells." (PMID 39544930, 2024). "However, more studies are required to establish the definitive role of IL-6 levels as potential prognostic and predictive biomarkers in various groups of melanoma patients." (PMID 39195270, 2024). "MDSCs were also reported to promote immune evasion in melanoma cells by inhibiting T cell activity and macrophage-mediated phagocytosis and to confer stemness properties to tumor cells by activating the IL-6/STAT3 signaling pathway." (PMID 39199632, 2024). "Several studies have suggested that IL-6 and CRP may be associated with diagnosis and prognosis of melanoma." (PMID 38952546, 2024). "Furthermore, during the metastasis of B16F-10 melanoma cells in mice, compound 4 dramatically reduced the serum levels of proinflammatory cytokines such IL-1β, IL-6, TNF-α, and GM-CSF." (PMID 38732642, 2024). "Microglial JAK/STAT activation from melanoma-secreted IL-6 can similarly enhance MBM progression." (PMID 38426087, 2024). "In addition, cytokines and chemokines such as IL6 and IL8 and CXCL1 participate in the crosstalk between cancer-associated fibroblasts and melanoma cells through paracrine signaling." (PMID 39494336, 2024). "There was no causal relationship between C-reactive protein and IL-6 on the risk of malignant melanoma." (PMID 38952546, 2024). "Therefore, we examined the expression of both, E2F1 and IL-6, and mesenchymal or epithelial cell markers in aggressive melanoma cells, and analyzed their correlation." (PMID 39544930, 2024). "In particular, gene expression profiling of B16-F10 melanoma cells reveals that mangiferin selectively inhibits expression, among others, of IL6, TNF, IFNG, VEGFR2, MMP19 and FGF1 genes with consequent deregulation of angiogenesis, cell viability and metastatic processes." (PMID 36768978, 2023). "Lastly, A375 displayed the most advanced stage of melanoma development by clear melanoma expansion into the reconstructed dermis and by the secretion of a plethora of (anti-)inflammatory cytokines (GM-CSF, IL-6, IL-8, IL-10, M-CSF, and TGFβ) involved in immune suppression and melanoma progression." (PMID 37345186, 2023). "Furthermore, pathophysiological levels of noradrenaline favor overexpression of VEGF, IL-8, and IL-6 in different human melanoma cell lines, and cytokine production are progressively increased in the metastatic phenotypes." (PMID 36766760, 2023).
melanoma (continued). "Moreover, ilexgenin A significantly inhibited the IL-6 (interleukin-6) production in macrophages stimulated by MCM (melanoma conditioned medium)." (PMID 38067491, 2023). "In view of the fact that IL-6 influences the morphology, gene expression, and secretome of microglia, we hypothesized that melanoma-derived IL-6 binds to its receptor expressed by microglia cells to initiate a signaling cascade through the IL-6/STAT3 pathway." (PMID 37296634, 2023). "UA could significantly inhibit the production of TNF-α, IL-1β, IL-6 and GM-CSF gene expression and production by B16F-10 melanoma cell in culture in a dose-dependent manner." (PMID 36768978, 2023). "Further, the pro-apoptotic activity of sulforaphane on highly metastatic melanoma cells was demonstrated and associated with a significant caspases activation and down-regulation of pro-inflammatory cytokines such as TNF-α, IL-6, IL-1β, IL-12p40, and GM-CSF in murine melanoma cells." (PMID 36768978, 2023). "Comparing IL-6 secretion levels in melanoma-microglia co-cultures with IL-6 secreted from melanoma and microglia mono-cultures demonstrated that the co-cultures of microglia with M12.CB3 and M16.CB3 melanoma cells secreted significantly higher amounts of IL-6 than the corresponding mono-cultures." (PMID 37296634, 2023). "The four melanoma cell lines used in the present study secrete IL-6." (PMID 37296634, 2023). "We next asked if IL-6 influences the cellular cross talk between melanoma and microglia." (PMID 37296634, 2023). "Our clinical observations corroborate the recently described prognostic association between plasma IL-6/CRP and poor survival of ICI-treated melanoma patients, and they identify high tumor IL6 expression as a predictor of poor atezolizumab monotherapy outcome in RCC." (PMID 36599350, 2023). "This suggests that IL-6 activates different pathways in melanoma 2D and 3D co-cultures." (PMID 37296634, 2023). "Moreover, IL‐6 level was correlated to early disease progression in melanoma patients receiving anti‐PD‐1 therapy." (PMID 38020717, 2023). "The results demonstrated that IL-6 was secreted from all four melanoma cell lines." (PMID 37296634, 2023). "IL-6 also influenced differentially the interaction of microglia with the different melanomas." (PMID 37296634, 2023). "Tissue expression of IL6 and its receptors increases with more advanced melanoma stage." (PMID 37551424, 2023). "The group also found that IL-6 may play a role in the stimulation of IL-10 production in melanoma cells." (PMID 35495152, 2022). "For example, in a retrospective analysis of patients with melanoma receiving immune checkpoint inhibitors, the IL-6 inhibitor tocilizumab was well-tolerated and an effective steroid-sparing treatment for the prevention and management of immune-related adverse events." (PMID 35538491, 2022). "This contradiction between our data on decreased IL-6 and IL-8 secretion by the keratinocytes treated by melanoma EVs and the bioinformatic analysis can be explained by the note that we studied cytokine secretion by the keratinocytes and modeled the local tumor microenvironment." (PMID 35327461, 2022). "Recent reports show a “bidirectional communication” between melanoma cells and adipocytes, especially in obese patients, consisting of the secretion of high amounts of pro-inflammatory factors such as IL-6, IL-11, TNF-α, monocyte chemoattractant protein (MCP)-1/CCL2, and PAI-1 by the excessive fat." (PMID 35334544, 2022). "Our findings are in line with an increasing body of evidence that the pro-inflammatory cytokine IL-6 can influence response to ICI in advanced melanoma, and further support a role of circulating HGF and MCP-2 levels as prognostic biomarkers as suggested by previous smaller studies." (PMID 36007304, 2022).
melanoma (continued). "To evaluate whether this enhanced IL-6 signaling mediated JAK1/2 activation, we blocked IL-6 and IL-6R with anti-IL-6 and anti-IL-6R antibodies, respectively, at concentrations that were sufficient to inhibit IL-6-induced p-STAT3 in melanoma cells." (PMID 36008408, 2022). "While our data suggest that IL-6, HGF, and MCP-2 retain independent association with ORR, the nature of the relationship between these three inflammatory proteins in the context of advanced melanoma remains to be elucidated." (PMID 36007304, 2022). "Since both melanoma and RCC are considered inflamed tumors, this data suggests that high sPD-L1 may be associated with different categories of inflammation (eg, IL6, TNFA, or complement-dependent) depending on the tumor type." (PMID 35131863, 2022). "Besides, we treated melanoma cells with 20 ng/ml IL-6 for different time points (0, 2, 6, 8, 12, 24, or 48 h)." (PMID 36188586, 2022). "In addition to paracrine signalling, exosomes produced by melanoma cells stimulated the production of IL-6 by CAFs, which improved in vitro migration of melanoma cells from the heterogeneous spheroids containing melanoma cells and CAFs in 3D collagen gels." (PMID 36429126, 2022). "Metastatic melanoma cells have been reported to exhibit elevated expression levels of IL-6." (PMID 36558948, 2022). "Importantly, dihydroartemisinin-mediated decrease of IL-10 and IL-6 in melanoma inhibited Treg polarization and infiltration in the TME." (PMID 36700235, 2022). "To test this hypothesis, we transiently transfected BRAFi-sensitive and BRAFi-R2 melanoma cells with two independent IL-6-targeting siRNA oligonucleotides to reduce IL-6 secretion and signaling." (PMID 36551563, 2022). "Here, we showed that EVs from the metastatic melanoma cells inhibit the release by keratinocytes of the IL6, IL8, IL10, and IL12 immunomodulatory cytokines and the regulators of cell adhesion and immune cell infiltration, such as sICAM-1, s-ICAM-3, sPECAM-1, sE- and sP-selectins, t-PA, and sCD40L." (PMID 35327461, 2022). "In addition to IL-6 secretion, metastatic melanoma cells can release IL-8 and VEGF under a β2-ADR-dependent catecholamines stimulation." (PMID 33923958, 2021). "Additionally, using melanoma cell line A375, growth was inhibited by IL6 in a STAT3-specific manner." (PMID 34411141, 2021). "Furthermore, IL-8 and IL-6 are released into the supernatant of highly invasive melanoma cell cultures." (PMID 34068618, 2021). "AGI-101H is a melanoma vaccine that relies on super-IL-6 transfected allogeneic melanoma cells." (PMID 33435427, 2021). "Since IL6 increases melanoma invasiveness and elevated levels of IL6 are linked with worse prognosis in non-responding patients, resulting effect of TNFα overexpression can be also adverse." (PMID 33957885, 2021). "Whereas 1205Lu melanoma cells induced with Palbociclib secrete IL6, IL8, and CXCL1." (PMID 34163519, 2021). "This growth inhibition could be enhanced with additional treatment with sIL6R, once more indicating a role of IL6 in mediating growth inhibition at early stages of malignant melanoma." (PMID 34411141, 2021). "IL6 is involved in melanoma, one of the major phenotypes of XP83." (PMID 33888761, 2021). "Similar to IL-1, IL-6 is abundant in the serum of patients with melanoma." (PMID 34604096, 2021). "In melanoma, the major histocompatibility complex proteins were transferred to the surface of antigen‐presenting cells to induce costimulatory immune receptors, to upregulate IL‐6, and to transfer TGF‐β." (PMID 33207034, 2021). "Furthermore, only melanoma samples from a location near adipocytes had IL-6 expression in the upper dermal regions." (PMID 34068679, 2021). "LAG-3+ pDCs possess tight contacts with melanoma cells and form IL-6 actively." (PMID 32902664, 2021). "Increased serum concentration of IL-6 has been correlated with a worse prognosis in patients with melanoma, even if the specific biological functions of IL-6 in progression of melanoma are unknown." (PMID 33467521, 2021).
melanoma (continued). "Thus, nuclear p-CREB (Ser133), IL6 expression, and IL6/STAT3 signaling were all restored upon S100B knockdown in WM115 melanoma cells." (PMID 34411141, 2021). "In addition, the activation of a subset of cytotoxic T cells, tumor-infiltrating lymphocytes, against melanoma tumors was enhanced by the use of IL6." (PMID 34411141, 2021). "In this study, we investigate whether NLRP3-dependent IL-1β production observed in melanoma cells drives IL-6/STAT3 signaling and whether this influences MDSC activity." (PMID 34531850, 2021). "A previous study conducted in melanoma demonstrated that IL-6 could upregulate the expression levels of CCR5 in MDSC through the STAT pathway, thus promoting their recruitment in the tumor microenvironment." (PMID 34975496, 2021). "Additionally, a study of melanoma patients receiving ipilimumab treatment showed that lower levels of circulating IL-6, IL-8 and sCD25 at baseline were significantly correlated with a higher incidences of colitis." (PMID 34732257, 2021). "With such data in mind, a model is discussed here in which elevated S100B may allow for melanoma cancer cells to escape immune detection by avoiding an early-stage IL6 dependent immune response in the tumor microenvironment." (PMID 34411141, 2021). "Importantly, IL-6 in the highly metastatic B16 melanoma F10 (B16-F10) cell line induces the production of GSH and its transport through the blood circulation to the brain metastatic growing foci, facilitating their growth in the brain." (PMID 33466236, 2021). "Furthermore, they reported that MVs from hypoxia-stimulated melanoma cells enhance fibroblast expression of IL-6, FAP and EGF, which are CAF markers." (PMID 34067929, 2021). "IL6 is involved in the progression and development of melanoma, but the specific function(s) remain unclear." (PMID 34411141, 2021). "For example, in melanocytes and early stages of melanoma, IL6 was shown to inhibit cell growth." (PMID 34411141, 2021). "Additionally, in a more aggressive melanoma cell line, higher levels of IL-6, eotaxin, and TNF-α were detected." (PMID 34068679, 2021). "Indeed, the elevated S100B levels in malignant melanoma cell lines correspond to low levels of IL6 and p-STAT3." (PMID 34411141, 2021). "However, it has been reported that the inhibition of the MAPK pathway can upregulate the PD-L1 expression, decrease IL-6 and IL-8 secretion, and increase the tumor-infiltrating lymphocytes in melanoma patients." (PMID 33692796, 2021). "Indeed, IL-17A promotes angiogenesis and induces IL-6 production in murine melanoma models, which in turn activates STAT3, upregulating the expression of angiogenesis and survival-supporting genes." (PMID 33466236, 2021). "On the other hand, measuring IL-6 together with a tumor marker under checkpoint inhibitor treatment might help to identify melanomas and other cancers depending on autocrine or paracrine IL-6 signaling." (PMID 32188047, 2020). "Interestingly, a recent report showed that the long-term survival of melanoma patients immunized with a Hyper-IL-6-modified allogeneic whole-cell vaccine was improved." (PMID 33287312, 2020). "Besides, melanoma TEV have been shown to induce IL-6 production in DC, leading to STAT3-dependent matrix metalloproteinase 9 production by tumor cells, promoting thereby their invasiveness." (PMID 32878277, 2020). "High levels of IL-6 secreted by melanoma metastases might mask the IL-6 protein signature deriving from immune activation." (PMID 32188047, 2020). "We found that the addition of recombinant human IL-6 protein in vitro and in vivo could reverse the inhibition of melanoma cell growth and migration by ATF3-overexpressing HDFs." (PMID 32373541, 2020). "Interestingly, elevated serum IL‐6 was correlated with a poor prognosis in melanoma, while IL‐4 is thought to promote the proliferation and survival of several cancer cells." (PMID 32485045, 2020).